NRAS (NRAS proto-oncogene, GTPase)
Diseases named in the same sentence as NRAS in open-access papers (continued):
Sharing a sentence is not in itself a finding about the gene and the disease.
melanoma (continued). "Notably, MEK1 mutations are often associated with either BRAF or NRAS mutations; however, the combinatorial effect of that association on the pathogenesis and treatment of melanoma has been poorly investigated." (PMID 30934534, 2019). "Due to high GC content of the TERT promoter, and this being a chronologically later mutational hit, we believe BRAF p.V600 and NRAS p.Q61/p.G12 variants to be the best pharmacodynamic biomarkers to monitor treatment response in mutation positive malignant melanoma patients." (PMID 31767937, 2019). "BRAF and NRAS mutations are also key drivers in many melanomas." (PMID 31861163, 2019). "However, the distribution is similar to what has been described in larger melanoma cohorts, where the Q61K and Q61R mutations were the most frequent NRAS mutations and distributed relatively equally." (PMID 30995742, 2019). "Moreover, rare activating mutations of ARAF have been identified in melanoma associated with an NRAS mutation, reinforcing the potential role of ARAF in NRAS-induced melanoma." (PMID 31398831, 2019). "Importantly, treatment of melanoma patient-derived xenografts, harbouring NRAS mutations, with a combination of a MEK inhibitor and a autophagy inhibitor, also significantly reduced the tumor burden." (PMID 31416288, 2019). "We also show that the atypical BRAF and NRAS mutations found in mucosal melanomas have particular effects on protein activities, which could be essential for the transformation of mucosal melanocytes." (PMID 31398831, 2019). "We then focused on the BRAF and NRAS melanoma driver gene mutations." (PMID 31795494, 2019). "However, the observation that DN tend to harbor non-V600E BRAF and NRAS mutations suggests that there are likely to be alternative pathways to Clark’s classically postulated model of a linear step-wise progression to melanoma." (PMID 31861163, 2019). "We found that NRAS exhibits distinctive codon mutations and amino acid substitutions in melanoma compared to hematopoietic and lymphoid tissue malignancies and thyroid cancers, as could be expected." (PMID 31398831, 2019). "In summary, the findings of the present study refine our understanding of the role of BRAF and NRAS mutations in mucosal melanomas and could pave the way for therapeutic intervention." (PMID 31398831, 2019). "Mutations of BRAF are found in about 65% of melanomas, while about 20% carry NRAS mutations." (PMID 31480477, 2019). "Biological and clinical evidence have showed that combination of ribociclib with MEK inhibitors as binimetinib or trametinib have increased anti-tumoral activity in neoplasias harboring NRAS mutations, including melanoma, NSCLC and colorectal carcinomas in preclinical models in vitro an in vivo." (PMID 29455659, 2018). "Nonetheless, 17-AAG inhibited melanoma cell proliferation regardless of BRAF mutational status, perhaps due to these cells’ dependence upon CRAF signaling in melanomas with activating NRAS mutations as well as activation of CRAF by BRAFWT under these conditions." (PMID 29481571, 2018). "In addition, either high MIFT-levels or a low MIFT/AXL-ratio were shown to be associated with resistance of BRAF-and NRAS-mutant melanoma cells towards kinase inhibitors and other targeted therapies." (PMID 29794999, 2018). "While many studies support the causal role of activating BRAF and NRAS mutations in melanoma progression, opposing data suggest that the contribution of PI3K-Akt pathway to this disease may be variable." (PMID 30166456, 2018). "Currently, detection of BRAF and NRAS mutations in ctDNA has shown significant value in predicting treatment response and outcome in melanoma and the recent inclusion of ctDNA analysis in clinical trials further highlights its imminent implementation in clinical practice." (PMID 29343260, 2018).
melanoma (continued). "This study aimed to explore whether melanoma patients with BRAF or NRAS mutant tumours have an increased risk of developing disease recurrence following a negative SLNB compared to patients with wild-type tumours." (PMID 29755118, 2018). "However, melanoma cell lines with NRAS mutations appeared to have a greater sensitivity than those with BRAF mutations." (PMID 29435161, 2018). "NRAS mutations lead to a substitution of the amino acids at positions G12 or G13 making NRAS insensitive to the inactivation by the Ras GTPase-activating proteins, or more common at position Q61, where Q61R is predominant in melanoma cells." (PMID 30360441, 2018). "In addition to Mel-Juso, we selected 2 additional cell lines with activating mutations in NRAS (SK-Mel-30 and SK-Mel-2) as well as 2 established melanoma cell lines with a BRAFV600E mutation (A375 and SK-Mel-28) for comparison." (PMID 29481571, 2018). "Other common mutations in melanoma (15–20%) are in the NRAS gene." (PMID 29371600, 2018). "BRAF, NRAS and Kit mutations stand out in pathogenesis and targeted therapy of melanoma." (PMID 29492238, 2018). "NRAS is the second most frequently mutated oncogene in melanoma." (PMID 29695835, 2018). "Recently, a tight interaction between PPP6C-AurkA and MAPK pathways in controlling proliferative activity and apoptosis in melanoma cells has been demonstrated, contributing to increase the levels of tumor heterogeneity and conferring a resistance signature in BRAF- and NRAS-mutated melanomas." (PMID 30218391, 2018). "In this report, we demonstrate that melanoma cells that either harbor activating NRAS mutations with BRAFWT or harbor the BRAFV600E mutation with wild-type NRAS, the BRAF is bound by HSP90 and under certain conditions is subject to degradation by HSP90 inhibition with 17-AAG." (PMID 29481571, 2018). "However, in late stage melanomas, longitudinal assessment of ctDNA levels, including BRAF and NRAS mutations in ctDNA, in melanoma patients receiving immunotherapy was predictive of response." (PMID 29343260, 2018). "In melanomas, NRAS mutations occur at a fairly consistent rate of 15–20%." (PMID 29682098, 2018). "Somatic mutations in NRAS account for approximately 26% of all malignant melanoma." (PMID 29650805, 2018). "In addition, the frequency of BRAF or NRAS mutations shows a melanoma subtype and metastatic site dependency." (PMID 30053879, 2018). "The second most prevalent oncogenic mutation in 20–25% of melanomas affects the NRAS gene." (PMID 29661909, 2018). "Importantly, cell proliferation and MAP kinase signaling were inhibited in three melanoma cell lines with NRAS activating mutations, Mel-Juso, SK-Mel-30, and SK-Mel-2, where BRAFWT was variably insensitive to 17-AAG." (PMID 29481571, 2018). "Moreover, the treatment with LY3009120 inhibited the growth of melanoma cells that harbor NRAS mutations xenografts and KRAS-driven colorectal tumors in vivo." (PMID 29455659, 2018). "Although mutational mechanisms may differ, these studies and our data support NF1 mutations being highly relevant in melanoma subgroups that rarely harbor BRAF or NRAS mutations." (PMID 28380455, 2017). "As most melanomas have copy number variations of whole chromosomes and of chromosome segment, NRAS mutant allele increase could be a consequence of chromosome instability and clonality in these tumors." (PMID 28668077, 2017). "However, paradoxical activation of the MAPK/ERK pathway by BRAF inhibitors is observed in NRAS-mutated melanoma and results from the recruitment of inhibited BRAF at the membrane where it acts as a scaffold to enhance CRAF activity." (PMID 28497782, 2017). "Additionally, 63 NRAS Q61 mutated melanomas, diagnosed before this period, were included into the molecular analyses." (PMID 28668077, 2017). "Accordingly, PLA experiments proved that not only CRAF but also BRAF could form complexes with NRAS in NRAS-mutated human melanoma cell lines." (PMID 28497782, 2017).
melanoma (continued). "Consequently, clinical mutation screening beyond BRAF and NRAS would be of significance in the clinical setting of melanoma." (PMID 28267273, 2017). "We hypothesize that High non-HET M%NRAS could have an oncogenic addiction effect, which could improve the sensitivity of targeted therapy in this subgroup of NRAS Q61 mutated melanoma." (PMID 28668077, 2017). "Furthermore, a recent study in melanoma indicates that RICTOR is frequently overexpressed and cooperates with NRAS mutation to stimulate melanoma proliferation." (PMID 28445935, 2017). "NRAS mutation in melanoma has been associated with aggressive tumor biology and poor prognosis." (PMID 28522871, 2017). "Sustained responses were observed mostly in BRAF or NRAS-mutated melanoma." (PMID 28954413, 2017). "We further demonstrated that Ets-1 promotes NRAS gene expression, which may at least partly underlie the high sensitivity of melanoma to Usp9x inhibition and Ets-1 depletion." (PMID 28198367, 2017). "Spitz tumors generally lack mutations in oncogenes classically associated with melanoma, such as NRAS, KIT, GNAQ, and GNA11, though distinct histopathologic forms have been found to harbor BRAFV600E and HRAS mutations, and suggest a role for activating kinase pathways in tumorigenesis." (PMID 28895885, 2017). "Taken together, these findings suggest that ARAF might be also an important player in NRAS-mutated melanoma under specific conditions." (PMID 28497782, 2017). "Approximately twenty percent of all melanomas have a hotspot mutation in the NRAS gene." (PMID 28350340, 2017). "We have established stable cell lines with NOXA knockdown using an shRNA-mediated approach, and found that knockdown of NOXA significantly protected against the combination-induced disruption of spheres (P<0.05) in both BRAF and NRAS mutated melanoma cell lines." (PMID 27086916, 2017). "Interestingly, we found that the EPE peptide was effective not only in reducing the viability of many BRAF mutant melanomas, but it also affected some cell lines bearing NRAS and/or NF1 mutations as well." (PMID 29180761, 2017). "Additionally, the genotyping accuracy of 40 NRAS mutated melanomas, 27 of which were p.Q61R was confirmed by immunohistochemistry with an antibody against Q61R." (PMID 28668077, 2017). "In addition to immunoediting, NRAS mutations decrease Fas receptor expression and the susceptibility to Fas-mediated apoptosis in melanoma." (PMID 28107203, 2017). "Interestingly, in case 4 we observed a BRAF V600E mutation in the primary melanoma, undetectable in the paired metastasis, which instead revealed a NRAS Q61R mutation." (PMID 28039443, 2017). "Indeed, BRAF mutations occur in 50–70% of all cutaneous malignant melanomas, whilst NRAS alterations only occur in 19–28% of tumours." (PMID 28637487, 2017). "Mutations in NRAS were identified in 26.6% of melanomas (124/466)." (PMID 27191502, 2016). "Taken together, these data strongly support the notion that evaluation of the oncogenic mutation (BRAF vs. NRAS) together with the expression of the ER subtype (ERβ vs. ERα) in melanoma patients should be taken into consideration when considering the most specific therapeutic approach to be applied." (PMID 27833586, 2016). "Upon our search, two samples in this database showed a CRAF mutation at position R391: one melanoma with R391S mutation (TCGA-EE-A20C, concurrent with a NRAS Q61R mutation) and one renal papillary cell carcinoma with R391W mutation (TCGA-B3-3925, without RAS mutation)." (PMID 27273450, 2016). "Moreover, high-frequency NRAS mutations occur in various tumors, such as melanoma, juvenile myelomonocytic leukemia and colorectal cancer." (PMID 27556696, 2016). "Because IFI6 is upregulated in NRAS-mutant melanoma, and its expression correlates with NRAS mutation status, this subgroup of melanoma could be targeted using this therapeutic approach." (PMID 27608486, 2016).
melanoma (continued). "In melanoma cells harboring activating NRAS mutation, RASA1 may play differential roles as a signaling adaptor/scaffold protein, since RASA1 cannot function as a RasGAP on mutated Ras isoforms." (PMID 26993606, 2016). "Interestingly, in this cohort, ZEB1 expression was higher in BRAFV600 or NRASQ61R‐mutated melanomas compared to BRAF/NRAS WT tumors, which corroborates the involvement of the MAPK pathway in the regulation of ZEB1." (PMID 27596438, 2016). "Localized immunotherapies exhibit enhanced activity in high-grade melanoma and may be especially effective in those with NRAS mutations." (PMID 27556696, 2016). "Thus, therapies were developed to specifically target (“targeted therapies”) melanomas harboring either the BRAF or the NRAS mutation." (PMID 27833586, 2016). "Moreover, we observed a secondary T790M EGFR mutation in lung adenocarcinoma (LUAD) and resistance to EGFR-targeted therapies (Gefitinib and Afatinib), as well as resistance of NRAS mutated melanoma patients to a BRAF inhibitor." (PMID 27397505, 2016). "The acquisition of TERT promoter mutation in BRAF or NRAS mutated melanoma probably allows the re-expression of TERT leading to the immortalization process on path to melanoma development, together with other alterations such as inactivation of cyclin-dependent kinase inhibitor 2A (CDKN2A)." (PMID 27449293, 2016). "Mutations in the NRAS oncogene are present in up to 20% of melanoma." (PMID 27608486, 2016). "Here we have examined a potential use of α-Mangostin, a naturally occurring organic xanthonoid compound which can be isolated from various parts of the mangosteen tree (Garcinia mangostana), as a potential combinatorial agent against an NRAS mutated melanoma cell line." (PMID 27152946, 2016). "Overall, NRAS mutations were detected in slightly less than a third (26.6%) of melanomas, and we found that NRAS mutations were much more frequent in melanomas of South Island patients (38.3%) than in North Island melanoma patients (21.9%), or in TCGA data (22%)." (PMID 27191502, 2016). "In summary, we discovered that the potential benefits of Sorafenib in combination with α-Mangostin might serve as a new therapeutic platform upon which to improve treatment of melanoma patients harboring NRAS mutations." (PMID 27152946, 2016). "Furthermore, melanomas harbouring NRAS or BRAF mutations were associated with a trend towards worse survival and a greater likelihood of brain metastases at the time of initial diagnosis." (PMID 27213536, 2016). "Additionally, IFI6 overexpression significantly correlated with the NRAS mutation status in patient-derived melanoma samples." (PMID 27608486, 2016). "A melanoma case had NRAS mutation co-occurring with PIK3CA mutation." (PMID 26435479, 2015). "In addition to BRAF, NRAS mutations, mostly affecting codon 61, are found in 10–15% of melanomas and are involved in mutagenic activation of the MAPK pathway." (PMID 26305188, 2015). "MiR-21-mediated inhibition of Sprouty may thus promote mutated BRAF/NRAS signaling of melanoma cells." (PMID 26116372, 2015). "However, to avoid the feedback or paradoxical activation of the MAPK pathway in NRAS mutated melanomas, the pathway was blocked at both RAF and MEK steps by using the combination of a PRi (Amgen Compd A) and a MEKi (trametinib)." (PMID 25645078, 2015). "TERT promoter mutations are known to be more common in BRAF or NRAS mutated tumors compared to WT melanomas and trend towards worse OS, however the role of TERT mutations in MBM is also unknown." (PMID 26597176, 2015). "For melanoma, the mPFS was 5.4 months in patients with NRAS mutation and 3.3 months in patients with NRAS wild type or NRAS status unknown." (PMID 25294187, 2015). "In this study we analysed the ctDNA in BRAF and NRAS-mutated melanoma patients at baseline (n = 48) and within 8 weeks of treatment initiation (n = 25) to determine whether ctDNA correlates with treatment response and clinical benefit." (PMID 26524482, 2015).
melanoma (continued). "Fourteen NRAS mutated human melanoma cell lines were treated with a pan-RAF inhibitor (PRi, Amgen Compd A), a MEK inhibitor (MEKi, trametinib) or their combination and the effects on proliferation, cell cycle progression, apoptosis, transcription profile and signaling of the cells were investigated." (PMID 25645078, 2015). "In melanoma patients, the ORRs were 20.0 % vs. 33.3 % between those with NRAS mutations (n = 10) and NRAS wild type/unknown (n = 9), respectively." (PMID 25294187, 2015). "Recent data suggested that NRAS mutation in melanoma was also a predictive factor for response to high-dose interleukin 2 indicating that immunotherapy could become the first-line treatment for NRAS-mutated metastatic melanomas, prior to MEK inhibition." (PMID 26204954, 2015). "The NRAS mutations are associated with a more aggressive clinical course in melanoma patients; tumors carrying such mutations may benefit of the simultaneous inhibition of the MAPK and PI3K pathways." (PMID 26322273, 2015). "This differential effect of ERβ agonists on the growth of the different melanoma cell lines might be related either to the specific oncogenic mutational status (NRAS, BRAF) or to the relative expression of receptor isoforms in each cell line." (PMID 26225426, 2015). "Eight of 20 (40.0 %) patients with HCC had a prior anti-VEGF treatment and 14 (70.0 %) of them were Child-Pugh A. Ten of 19 (52.6 %) melanoma patients had NRAS mutation, one (5.3 %) was wild type, and eight (42.1 %) were unknown." (PMID 25294187, 2015). "Moreover, Cox regression analysis revealed that NRAS mutation was the only predictive factor of shorter survival from primary melanoma (p = 0.039, OR = 5.5 (1.1–27.6))." (PMID 26305188, 2015). "There is limited published data on the molecular alterations associated with MBM, although in general, debate in the literature exists as to whether BRAF and/or NRAS mutated melanomas are associated with worse survival outcomes compared to WT tumors." (PMID 26597176, 2015). "Indeed, we found that the locus coding for RICTOR is frequently amplified in melanoma independently of BRAF or NRAS mutations and that RICTOR amplification in BRAF mutated melanoma is associated with PTEN LOH." (PMID 26356562, 2015). "Activated PI3K-AKT pathway may contribute to decrease sensitivity to inhibitors of key pathogenetic effectors (mutated BRAF, active NRAS or MEK) in melanoma." (PMID 25627962, 2015). "Among them, NRAS mutations are the most detected in melanoma." (PMID 26322273, 2015). "In addition to BRAF, NRAS is mutated in 15–25% of all melanomas, most frequently in exon 1 (G12) and exon 2 (Q61)." (PMID 26426340, 2015). "NRAS mutations in non-melanoma tumors have an important clinical impact on the overall population." (PMID 25277205, 2014). "Oncogenic mutations in BRAF and NRAS occur in 70% of melanomas." (PMID 24550252, 2014). "Our results suggest that inhibitor combinations targeting the MAPK and PI3K/AKT/mTOR pathways downstream of NRAS may be a potential treatment option for non-melanoma tumors harboring activating NRAS mutations." (PMID 25277205, 2014). "Only a few trials specifically target melanomas with NRAS mutations, but a number of trials use combinations of agents or single agents that could have therapeutic benefits in this subgroup of melanoma." (PMID 24743024, 2014). "Our results suggest that such inhibitor combinations may be a potential treatment option for non-melanoma tumors harboring activating NRAS mutations." (PMID 25277205, 2014). "Furthermore, this paper also gives mutation frequencies of BRAF (25%) and NRAS (10%) that are quite different from most studies in the melanoma field." (PMID 25593912, 2014). "Approximately 20% of melanomas have mutations in the GTPase NRAS." (PMID 24743024, 2014). "Interestingly, a genetic abnormality in one melanoma patient was the NRAS mutation, whereas the other two patients harbored the BRAF V600E mutation." (PMID 25422890, 2014).